TRIM41 (tripartite motif containing 41)
Description:
E3 ligase that plays essential roles in innate antiviral response. Directly binds to influenza A virus or vesicular stomatitis virus nucleoproteins and targets them for ubiquitination and proteasomal degradation, thereby limiting viral infections. Activates the innate antiviral response by catalyzing monoubiquitination of CGAS, thereby activating CGAS. Also involved in innate antiviral response by mediating 'Lys-63'-linked polyubiquitylation of BCL10 which in turn hubs NEMO for activation of NF-kappa-B and IRF3 pathways (By similarity). Catalyzes the ubiquitin-mediated degradation of other substrates including protein kinase C, ZSCAN21 or TOP3B suggesting additional roles besides its function in immune response.
Synonyms: RINCK; MGC1127
Tractability: PROTAC: UniProt records ubiquitination sites on it; ubiquitination databases record sites on it; its protein half-life has been measured.
Gene: Protein-coding gene on chromosome 5 (181,222,499 to 181,235,808, forward strand). Ensembl gene ENSG00000146063.
Subcellular location: Cytoplasm; Nucleus
Subcellular location (Human Protein Atlas): Nucleoli fibrillar center; Cytosol; Nucleoplasm; Vesicles
Pathways (Reactome):
Immune System: Antigen processing: Ubiquitination & Proteasome degradation
Gene Ontology:
Molecular function: identical protein binding; protein binding; ubiquitin protein ligase activity; zinc ion binding
Biological process: cellular response to lipopolysaccharide; cellular response to muramyl dipeptide; defense response to virus; positive regulation of type I interferon-mediated signaling pathway; protein monoubiquitination; innate immune response; positive regulation of signal transduction; protein ubiquitination
Cellular component: cytoplasm; cytosol; fibrillar center; nucleoplasm; nucleus
Genetic constraint (gnomAD): Loss-of-function variants: 21 observed, 63.01 expected, observed/expected ratio (o/e) 0.33, 90% interval 0.23 to 0.48. The upper end of that interval is the gene's LOEUF score, 0.48, which puts it in group 2 of 6, group 1 being the genes least tolerant of losing a copy. Missense variants: 846 observed, 898.86 expected, observed/expected ratio (o/e) 0.94, 90% interval 0.89 to 1. Synonymous variants: 407 observed, 358.46 expected, observed/expected ratio (o/e) 1.14, 90% interval 1.05 to 1.23.
Homologues: Orthologues: macaque TRIM41 (99% identical), chimpanzee TRIM41 (99% identical), dog TRIM41 (98% identical), pig TRIM41 (98% identical), rat Trim41 (94% identical), mouse Trim41 (94% identical), guinea pig TRIM41 (94% identical), zebrafish si:dkey-29p10.4 (19% identical). Paralogues in human: TRIM11 (29% identical), TRIM27 (29% identical), TRIM39 (29% identical), TRIM52 (29% identical), TRIM17 (27% identical), TRIM7 (26% identical), TRIM58 (25% identical), TRIM21 (25% identical), TRIM10 (25% identical), TRIM26 (24% identical), TRIM4 (24% identical), TRIM15 (22% identical), and 68 more.
Diseases named in the same sentence as TRIM41 in open-access papers:
TRIM41 is named in the same sentence as 18 diseases in open-access papers, as found by Europe PMC text mining. Sharing a sentence is not in itself a finding about the gene and the disease. The quoted sentences say what the papers report.
viral infection (4 papers, 2017 to 2024). "As further evidence for TRIM41-mediated virus-triggered interferogenic response, we found that TRIM41 deficiency impaired the induction of interferon-stimulated genes (ISG), such as Cxcl10, Ccl5, and Ifi202b, by virus infections." (PMID 33640899, 2021). "We previously reported that TRIM41 interacted with influenza viral protein to limit viral infection." (PMID 31979016, 2020). "Since the innate response to pathogenic nucleic acids and virus infection has been impaired in Trim41−/− BMDM and BMDC, we further focused on investigation of TRIM41-mediated innate antiviral defense by using VSV, Listeria monocytogenes (LM) and HSV-1 infection models." (PMID 33640899, 2021). "Therefore, it is plausible that TRIM41 also interacts with VSV protein(s) to inhibit viral infection." (PMID 31979016, 2020). "Secondly, TRIM41 is an intrinsic immunity factor that inhibits viral infection." (PMID 31979016, 2020). "Reporter assays demonstrated the increased viral infection in TRIM41 knockout cells." (PMID 31979016, 2020). "We further examined the co-localization of endogenous TRIM41 and VSV-N during viral infection." (PMID 31979016, 2020). "Consistently, PKP2, FKBP8, TRIM41 and ZMPSTE24 inhibited viral infection of NY/2009 and WSN/33." (PMID 28169297, 2017).
hepatoma (2 papers, 2013 to 2019). "Our studies have thus identified eight TRIM proteins that are able to inhibit HBV transcription and provided strong evidences suggesting the endogenous role of TRIM41 in regulating HBV transcription in human hepatoma cells." (PMID 23936368, 2013). "Moreover, endogenous TRIM41 plays a role in regulation of HBV transcription in human hepatoma cells." (PMID 23936368, 2013). "TRIM41 blocks the transcription and replication of hepatitis B virus (HBV) by inhibiting the enhancer II activity of HBV in human hepatoma cells." (PMID 31126132, 2019).
melanoma (2 papers, 2022). A malignant, usually aggressive tumor composed of atypical, neoplastic melanocytes. "Studies have reported that the expression of ANXA10 is significantly increased in melanoma and can promote melanoma metastasis by suppressing E3 ligase TRIM41-directed PKD1 degradation." (PMID 35693827, 2022). "ANXA10 boosts melanoma metastasis via inhibiting E3 ligase TRIM41-directed PKD1 degradation." (PMID 36158697, 2022).
airway allergy (1 paper, 2024). "The purpose of this study is to analyze the role of TRIM41 in the pathogenesis of airway allergy (AA) and the impact of regulating TRIM41 on suppressing AA." (PMID 38883815, 2024).
asthma (1 paper, 2020). "They include RBM42, STX5, and TRIM41 in asthma, CYP27A1, GM2A, LGALS9, SPI1, and NLRC4 in COPD, as well as ATF3, PPP1R15A, ZFP36, SOCS3, NAMPT, and GADD45B in IPF." (PMID 31952466, 2020). "According to the results, RBM42, STX5, and TRIM41 may have critical functions in asthma." (PMID 31952466, 2020). "These genes included RBM42, STX5, and TRIM41 in asthma, CYP27A1, GM2A, LGALS9, SPI1, and NLRC4 in COPD, ATF3, PPP1R15A, ZFP36, SOCS3, NAMPT, and GADD45B in IPF, LRRC48 and CETN2 in asthma-COPD, COL15A1, GIMAP6, and JAM2 in asthma-IPF and LMO7, TSPAN13, LAMA3, and ANXA3 in COPD-IPF." (PMID 31952466, 2020).
colorectal carcinoma (1 paper, 2025). A malignant epithelial neoplasm that arises from the colon or rectum and invades through the muscularis mucosa into the submucosa. "In HCT116 cells (human colorectal carcinoma) and HEK293 cells, stable TOP3B covalent intermediates that remain unresolved are reported to be targeted by the E3 ubiquitin (Ub) ligase TRIM41 and subsequently degraded by the proteasome." (PMID 41189056, 2025).
Infertility (1 paper, 2022). "Unexpectedly, Trim41 deficiency caused meiosis defects and infertility in male mice despite ubiquitous expression." (PMID 35648791, 2022). "However, unexpectedly, Trim41 KO male mice exhibited complete infertility due to meiotic defects." (PMID 35648791, 2022).
influenza (1 paper, 2019). An acute viral infection of the respiratory tract, occurring in isolated cases, in epidemics, or in pandemics; it is caused by serologically different strains of viruses (influenzaviruses) designated A, B, and C, has a 3-day incubation period, and usually lasts for 3 to 10 days. "More recently, TRIM41 has shown to likewise target viral NP for degradation, to such an extent that TRIM41 deficiency increases host susceptibility to influenza." (PMID 30857287, 2019).
Testicular atrophy (1 paper, 2022). Wasting (atrophy) of the testicle (the male gonad) manifested by a decrease in size and potentially by a loss of fertility. "To define the cause of testicular atrophy, we performed hematoxylin and periodic acid-Schiff (HePAS) staining of testicular sections and found that the germ cell layer was thinner in Trim41 KO testis than in control testis (low magnification)." (PMID 35648791, 2022).
Turner syndrome (1 paper, 2022). Turner syndrome is a chromosomal disorder associated with the complete or partial absence of an X chromosome. "Therefore, Trim41-deficient XO meiosis (i.e. mouse model of Turner Syndrome) might be an intriguing future consideration." (PMID 35648791, 2022).
cancer (3 papers, 2018 to 2023). A tumor composed of atypical neoplastic, often pleomorphic cells that invade other tissues. "Whether genetic Trim41 variations are involved in cancer also need further investigations." (PMID 33640899, 2021). "Moreover, TRIM41 has been reported to mediate degradation of various PKC isoforms, including the widely expressed PKCα, which themselves regulate cancer cell proliferation under various conditions." (PMID 29568378, 2018). "However, genomic variations in Trim41 has not been reported in inflammatory diseases, but has been deposited in TCGA, Oncomine, and International Cancer Genome Consortium databases for cancer patients." (PMID 33640899, 2021).
infection (3 papers, 2020 to 2021). The state of being infected such as from the introduction of a foreign agent such as serum, vaccine, antigenic substance or organism. "TRIM41 deficiency impairs the production of inflammatory cytokines and type I interferons in macrophages after transfection with nucleic acid-mimics and infection with both DNA and RNA viruses." (PMID 33640899, 2021). "TRIM41 knockout cells were more susceptible to the single cycle infection than wild type cells, suggesting that TRIM41 limits VSV infection by targeting the VSV-N of incoming virus." (PMID 31979016, 2020). "TRD7 and TRIM41 were suppressed during initial infection and also found in the clearance states of Mtb." (PMID 34141493, 2021). "Expression of TRIM41 was 12.44-fold lower in H37Rv infection compared to uninfected controls." (PMID 34141493, 2021). "TRIM41 or the Del-RING was transfected into HEK293 cells, followed by infection with different MOIs of VSV-Luc for 16 h." (PMID 31979016, 2020). "After infection with HSV-1, Trim41 mRNA and protein were also downregulated." (PMID 33640899, 2021).
TRIM41 also shares sentences with these, for which no sentence is quoted: Parkinson disease (2 papers); tumor (2); Arthritis (1); Epstein-Barr virus infection (1); fragile X syndrome (1); psoriasis (1).